LGALS3 (galectin 3)
Diseases named in the same sentence as LGALS3 in open-access papers (continued):
Sharing a sentence is not in itself a finding about the gene and the disease.
infection (continued). "New findings explored in this review focus on the chronic phase, when wild-type (Lgals3+/+) and Lgals3-/- mice were analyzed 90 days after cercariae infection." (PMID 28231240, 2017). "Our data suggest that a high expression of IL-4 in isolated GR-HSCs from Lgals3-/- reinforces the immunomodulatory role of these cells, interfering with Th1/Th2 balance during the chronic phase of infection." (PMID 28231240, 2017). "Galectin-3 (Gal-3) and its specific ligands were over-expressed in splenic DCs after infection by T. cruzi Tehuantepec strain, which lead to DC increased adhesiveness and reduced migration." (PMID 27471496, 2016). "Even though epithelial cells released galectin-3 in response to CPI-GC, within 24 h of infection the parasite significantly depleted the total and intracellular stores of galectin-3 thus evading the protective host inflammatory reaction." (PMID 26589797, 2016). "Reduction of galectin-3 expression on corneal keratinocytes reduced HSV-1 binding and infection of the cells, indicating that galectin-3 can directly promote HSV-1 infection of target cells." (PMID 24995007, 2014). "All Lgals3−/− mice showed a logarithmic decrease in stool shedding at day 15, showing resolution of infection." (PMID 25243744, 2014). "In order to investigate the importance of Gal-1 and Gal-3 in mucosal immune responses to infection, Lgals1−/− and Lgals3−/− mice were infected with the enteric pathogen Citrobacter rodentium." (PMID 25243744, 2014). "The immune responses of Lgals1−/− and Lgals3−/− mice to infection are presented separately for clarity." (PMID 25243744, 2014). "Unexpectedly, we found that Lgals1−/− mice had diminished T cells and macrophages in the colonic lamina propria during infection with C. rodentium as compared to wild type mice and similarly to Lgals3−/− mice." (PMID 25243744, 2014). "While a direct anti-microbial mechanism was not determined in this study, galectin-3 null mice had a reduced capacity to clear M. tuberculosis late in infection, suggesting that galectin-3 had anti-microbial activity." (PMID 24995007, 2014). "As TNFα is a critical cytokine that promotes parasite clearance, the direct interaction of galectin-3 and T. gondii GPIs is an important initial step to reduce the extent of infection." (PMID 24995007, 2014). "While not directly blocking viral entry, the Panjwani and Argüeso labs found that galectin-3 can bind to ocular mucins to contribute to the barrier function of ocular mucins in preventing infection." (PMID 24995007, 2014). "The survival advantage of F. novicida infected galectin-3−/− was observed to be only transient as these mice ultimately succumbed to infection, possibly due to overwhelming bacterial burdens." (PMID 23527230, 2013). "Notwithstanding the mechanism involved, release of galectin-3 in the septic phase of F.n. infection indicates a role for this molecule in pathogenesis of this infection." (PMID 23527230, 2013). "Galectin-3−/− macrophages on the other hand, produced significantly lower amounts of these cytokines in response to infection." (PMID 23527230, 2013). "The galectin-3−/− mice succumbed to the infection at a similar rate as WT mice when infected with 300–500 CFUs of bacteria (data not shown)." (PMID 23527230, 2013). "Intriguingly, enumeration of bacterial burden in the organs of these mice at the peak of infection, i.e., 3 d.p.i. showed that both galectin-3−/− and the wild-type animals exhibited similar bacterial burdens in their systemic organs as well as in blood." (PMID 23527230, 2013). "Prior to cellular infection the infective trypomastigotes bombard host cells with PLC-cleaved gp83 to activate the ERK1/2 pathway to up regulate laminin primed cells to enhanced infection via the laminin-45 mucin-galectin-3 pathway." (PMID 23133440, 2012).
infection (continued). "On the other side, triggering gp83 receptors in the cell via ERK1/2 cross-talk with the THBS1 sub-network, also enhances cellular infection and cross-talk at a distance with LGALS3, which also recruit parasites via Tc45 mucin, and LAMC1." (PMID 23133440, 2012). "In this work, we showed that the basic structural aspects of the MLNs of galectin-3−/− mice were softly disturbed independently of the infection." (PMID 21573150, 2011). "First, we evaluated galectin-3+ cells in the MLNs of uninfected and infected mice in the chronic phase of S.mansoni-infection." (PMID 21573150, 2011). "In the past few years, the immunity to several infections has been demonstrated to be influenced by galectin-3, the most studied member of the galectin family." (PMID 19229338, 2009). "The R. equi model of infection has revealed galectin-3's ability to exert a regulatory role in innate immunity by diminishing macrophage IL-1β production." (PMID 19229338, 2009). "To better evaluate the effect of galectin-3 in the mechanisms of resistance to P. brasiliensis infection, we measured the pulmonary NO levels in the infected mice 30 days after infection." (PMID 19229338, 2009). "In a majority of these infections, the role of galectin-3 appears to depend on direct interaction with the parasite." (PMID 19710907, 2009). "There is recent evidence that galectin-3 participates in immunity to infections, mostly by tuning cytokine production." (PMID 19229338, 2009). "Galectin-3, a beta-galactoside-binding lectin weighing between 29 and 35 kDa, is recognized for its role in amplifying infection impact through fostering inflammatory reactions in the host and facilitating the secretion of diverse cytokines such as IL-6 and TNF-alpha." (PMID 38674175, 2024). "We also found that Lgals3−/− mice were protected against primary infections with CEP Δpigj, indicating a fundamental role of galectin-3 in the susceptibility of wild-type mice to CEP Δpigj infections." (PMID 39302131, 2024). "Interestingly, Lgals3−/− mice had higher Th1 responses with increased IL-12p40 and IFNγ detected in the sera, as well as from cultured splenocytes after infection." (PMID 39302131, 2024). "However, while bacterial clearance was significantly impaired in the LPS pre-exposed galectin-3 KO mice with the mice appearing sick and huddled early after infection, they subsequently recovered after 24 h resuming normal activity." (PMID 38830855, 2024). "Therefore, we were interested in the proteolytic processing of galectin-3 by meprin α/β heterodimers upon infection and the subsequent inflammation." (PMID 37000885, 2023). "(E–F) Automated quantification of the relative proportion of GFP +objects co-localized with IF staining for Galectin-3 (E) or P62 (F) as a function of time post-infection for n=3 donors, normalized to wild-type (H37Rv) (* p<0.05, ** p<0.01, *** p<0.001; paired t-test)." (PMID 37073954, 2023). "Galectin-3’s role in mediating tissue damage and inflammation highlights its importance in the complex interplay between the host immune system and viral pathogens during various infections." (PMID 37298569, 2023). "Quantification of galectin-1 and galectin-3 secreted from hVECs and HeLa cells before and post-infection revealed that both galectins were secreted at much higher levels from hVECs than HeLa cells, explaining why the swarming phase was less observed in HeLa cells on infection." (PMID 36595499, 2023). "infection with the presence of galactose in the backbone structure of the capsular components of the fungus, so it ends up contributing to the fight against infection by cellular activation via the interaction of the capsular components with galectin-3." (PMID 35736250, 2022). "Galectin-3 is a multi-role protein that was originally identified in the response to infection." (PMID 36615679, 2022). "Galectin-3 regulates the anti-infection immune signaling pathway in fungal keratits." (PMID 35437453, 2022).
infection (continued). "Infection with Listeria and Streptococcus induces galectin-3 accumulation and inhibits selective autophagy for bacterial clearance, suggesting that different pathogens hijack intracellular galectin-3 during infection and modulate cellular autophagy for replication." (PMID 33663512, 2021). "However, experimental models of chronicity spilled over the idea that galectin-3 was modulated only during the early stages of infection." (PMID 35046919, 2021). "Infected galectin-3-depleted cells showed not only loss of mitochondrial membrane potential but also an increase in caspase-3 activity and elevated proteolytic processing of poly (ADP-ribose) polymerase after 4 and 8 h post-infection." (PMID 35046919, 2021). "Furthermore, Galectin-3 deletion in C57Bl/6 mice reduced the number of activated immune cells after TMEV infection and diminished inflammatory response followed by a partial restoration of SVZ proliferation and increase of SVZ progenitor cells." (PMID 32455781, 2020). "Furthermore, we demonstrated that galectin-3 facilitated HIV-1 CRF07_BC infection, which was mainly via the CRD interacting with viral gp120 and cellular CD4." (PMID 32485969, 2020). "This phenomenon was further confirmed by using clinical isolates, subtype B (TW_B) and CRF07_BC (TW_CRF07_BC) infected MDMs, demonstrating that TW_CRF07_BC infection induced a significantly higher galectin-3 expression detected in mRNA and supernatant proteins compared to the mock (p < 0.01)." (PMID 32485969, 2020). "Furthermore, we found that HIV-1 CRF07_BC infection induced galectin-3 expression in the monocyte-derived macrophage (MDM), as well as, significantly triggered galectin-3 secretion to the culture medium compared to the mock (p < 0.01)." (PMID 32485969, 2020). "Thus, this study aims to address the correlation of galectin-3 to CRF07_BC infection and the potential effect of amino acid deletions on the p6Gag on galectin-3-mediated regulation." (PMID 32326345, 2020). "We found that both mice and humans produce galectin-3 when infected with A. fumigatus, and mice lacking galectin-3 were more susceptible to infection than normal mice." (PMID 32750085, 2020). "Galectin-3 levels were elevated in the serum of wild-type mice after 72 hours after infection." (PMID 32750085, 2020). "Induction of galectin-3 expression and the galectin-3-dependent Alix-promoting effect on budding step during HIV-1 CRF07_BC infection are two different events, which might occur through different regulatory pathways." (PMID 32326345, 2020). "We therefore hypothesized that galectin-3 plays a role in HIV-1 CRF07_BC infection and amino acid deletions in the p6Gag may affect the regulation induced by galectin-3." (PMID 32326345, 2020). "During infection, galectin-3 has been reported to mediate host defense against microbes through multiple mechanisms including binding to, and directly killing pathogens, mediating pathogen detection through cross-linking canonical immune receptors, and/or enhancing immune cell recruitment." (PMID 32750085, 2020). "We suggested that HIV-1 CRF07_BC infection prompts galectin-3 expression." (PMID 32326345, 2020). "In this study, we address the potential roles of galectin-3 in HIV-1 CRF07_BC infection." (PMID 32485969, 2020). "We also demonstrated that CRF07_BC infection triggered galectin-3 expression and secretion." (PMID 32485969, 2020). "In addition, following a primary infection, the LGALS3 gene in the HSF flock and the LGALS3BP gene in the TSF flock were significantly induced in the abomasum of resistant sheep." (PMID 30678719, 2019). "If so, it may be worth testing whether galectin-3 injections during a bacterial infection help clear the infection by opsonizing the bacteria." (PMID 31781126, 2019). "In view of its upregulation in MHV68-specific TCR TN CD8+ T cells, we investigated whether galectin-3 expression has a functional consequences in resolving the infection." (PMID 30388704, 2018).
infection (continued). "The role of galectin-3 in CD8+ T cells during a γ-HV infection is thus cell autonomous." (PMID 30388704, 2018). "Targeting intracellular galectin-3 in CD8+ T cells may therefore serve to enhance response to efficiently control infections." (PMID 30388704, 2018). "The protein Galectin-3 modulates host immunity and plays roles during infections." (PMID 29213074, 2017). "Indeed, considering that the first step of the infection is under the control of a macrophage, the outcome of the disease needs to be further investigated, including in the Lgals3-/- infected mice." (PMID 28231240, 2017). "Infection with MuLV increased the levels of galectin-3 and -6 in PrP+/+ cells." (PMID 27936017, 2016). "Indeed, galectin-3 and cholesterol, a membrane component, localized with Toca-1 in the vicinity of intracellular S. flexneri at this early infection time." (PMID 24722587, 2014). "Although speculative at this stage, it is possible that the activating receptor for galectin-3 on neutrophils is constitutively expressed while that on macrophages likely gets expressed in an infection-specific manner." (PMID 23527230, 2013). "Galectin-3 relocalization has therefore been utilized as a tool to identify ruptured vesicles in studies of bacteria and viruses which rely on vesicle rupture to enter the cytoplasm during infection." (PMID 23634225, 2013). "Consistent with characteristic properties of alarmins, galectin-3 was upregulated and extracellularly released during the septic phase of infection and could amplify the Francisella infection-induced inflammatory response of neutrophils and macrophages." (PMID 23527230, 2013). "Interestingly, this survival advantage of galectin-3−/− mice was dependent on the infection dose of bacteria." (PMID 23527230, 2013). "However, in F.n. infection, this lectin is likely released passively from dead/dying cells since the extracellular galectin-3 is detected only during lethal infection with F.n., which typically results in extensive cell death." (PMID 23527230, 2013). "Silencing the expression of LGALS3 also reduces cellular infection." (PMID 23133440, 2012). "Thus, galectin-3 provides a bridge between parasites and laminin in host cell thereby enhancing infection." (PMID 23133440, 2012). "The studies of infection with the intracellular bacteria Rhodococcus equi have demonstrated that galectin-3 may regulate the innate immune response by diminishing IL-1β production by macrophages." (PMID 19229338, 2009). "The results presented here, together with previous observations on the role exerted by galectin-3 in several infections, allow us to postulate that regulation of the Th1/Th2 balance by galectin-3 changes with the diversity of the initial responses triggered by different pathogens." (PMID 19229338, 2009). "These investigations were performed by comparing the course of experimental infections in mice that were genetically deficient, or not, in galectin-3." (PMID 19229338, 2009). "Similarly, galectin-3 levels, which increase in both epithelial and stromal compartments during infection, correlate with enhanced proliferative signaling and resistance to apoptosis, suggesting its potential as a biomarker for identifying individuals at higher risk of gastric carcinogenesis." (PMID 40806347, 2025). "The question of whether the absence of galectin-3 leads to increased susceptibility to infection in mice remains to be determined." (PMID 38830855, 2024). "Furthermore, Galectin-3 can impede the growth of Paracoccidioides brasiliensis and diminish the stability of its extracellular vesicles, thereby playing a crucial role in defending the host against pathogen infections." (PMID 37511297, 2023). "The recruitment of the glycan binding proteins galectin-3, -8, and -9 to a population of R. equi indicates that the R. equi-containing vacuole is damaged to the extent that luminal glycans are exposed to and recognized by cytosolic danger sensors as early as 4h post infection." (PMID 34473814, 2021).
infection (continued). "As neutrophils play a critical role in the innate defense against A. fumigatus infection, we hypothesized that galectin-3-mediated neutrophil migration to the site of infection is the primary mechanism by which this lectin contributes to host resistance against this organism." (PMID 32750085, 2020). "We further addressed whether galectin-3 plays a role in HIV-1 CRF07_BC infection." (PMID 32485969, 2020). "Moreover, infection didn't increase NK cell frequency in Lgals3−/− mice." (PMID 31231399, 2019). "As T. cruzi infection increases expression of ECM components such as laminin by host cells, the parasite may use the bridging function of galectin-3 to accumulate in the basement membranes surrounding host target cells such as cardiac myoblasts, thus increasing the likelihood of infection." (PMID 24995007, 2014). "We thus hypothesized that galectin-3 exacerbates the inflammatory response during lethal infection." (PMID 23527230, 2013). "We also introduce galectin-3, a chimera type of the galectin family that is up-regulated by HIV-1 during infection and further used to promote HIV-1 assembly and budding via the stabilization of Alix–Gag interaction." (PMID 35891508, 2022). "Results indicated that galectin-3 were significantly induced after HIV-1 CRF07_BC and NL4-3 infection (p < 0.01) and higher amounts of mRNA and protein of galectin-3 were detected in CRF07_BC than B (p < 0.01)." (PMID 32326345, 2020). "It was ascertained that galectin-3 and -8, as well as galectin-1 and -7, colocalized with GAS-surrounding Tollip at 4 h post-infection." (PMID 33425778, 2020). "Our results indicate that galectin-3 binds to gp120 and CD4 proteins via the CRD, further facilitating HIV-1 CRF07_BC infection." (PMID 32485969, 2020). "As expected, infection upregulated the expression of several inflammation-related genes, including TNF-α, IFN-γ, IL-1β, galectin-3, TGFβ, and IL-10, compared to naïve controls." (PMID 31244833, 2019). "Our RNA-seq data showed upregulation of two members of the galectin family, i.e., galectin-3 (up ∼140-fold) and galectin-1 (up ∼87-fold), in activated TN CD8+ T cells during the acute phase of infection with MHV68." (PMID 30388704, 2018). "Galectin-3 localized within the LCV and did so similarly to the manner seen with infection with WT L. pneumophila, indicating that the T2S system is not required for the permeable LCVM." (PMID 28634242, 2017). "Previous studies have shown that fibronectin and galectin-3 can enhance HIV-1 entry and infection up to 20 fold." (PMID 29093555, 2017). "This phenomenon was observed in infection with both WT and mutant parasites, suggesting a mechanism independent from CPI-GC binding to galectin-3, because the mutant CPI-GC affinity to galectin-3 was drastically reduced." (PMID 26589797, 2016). "In galectin-3 null cells, the released and intracellular EV71 viral loads were suppressed after 24 h of infection, and cell death rates were significantly lower, while cell proliferation remained unaltered." (PMID 28002441, 2016). "At the same time, by depleting the levels of galectin-3, T. vaginalis diminishes the LPG pattern recognition through this galectin, which mediates the normal clearance of infection via chemokine-mediated neutrophil and macrophage recruitment." (PMID 26589797, 2016). "Compared with uninfected mice, infected wild-type mice showed higher levels of IL-4, IL-10 and IL-13, with similar levels of α-smooth muscle actin, galectin-3, TGF-β1, IL-17, IFN-γ, and lower IL-12 levels at 90 days post-infection." (PMID 25032961, 2014). "The fact that galectin-3 is secreted by macrophages and by other cells, including HCASM cells, suggests that released galectin-3 modulates infection via laminin." (PMID 23133440, 2012). "Infective trypomastigotes use Tc85 to interact with laminin, p45 mucin to interact with LAMC1 through galectin-3 (LGALS3), a human lectin, and calreticulin (TcCRT) to interact with TSB1 to enhance cellular infection." (PMID 23133440, 2012).